C14orf39 (chromosome 14 open reading frame 39)
Description:
Meiotic protein that localizes to the central element of the synaptonemal complex and is required for chromosome synapsis during meiotic recombination. Required for the appropriate processing of intermediate recombination nodules before crossover formation.
Synonyms: SIX6OS1; POF18; SPGF52
Tractability: PROTAC: ubiquitination databases record sites on it.
Gene: Protein-coding gene on chromosome 14 (60,396,469 to 60,515,543, reverse strand). Ensembl gene ENSG00000179008.
Subcellular location: Chromosome
Subcellular location (Human Protein Atlas): Nucleoli; Nucleoplasm
Gene Ontology:
Molecular function: protein binding
Biological process: homologous chromosome pairing at meiosis; meiotic DNA double-strand break processing involved in reciprocal meiotic recombination; oogenesis; spermatogenesis; meiotic cell cycle; synaptonemal complex assembly
Cellular component: central element; chromosome
Genetic constraint (gnomAD): Loss-of-function variants: 19 observed, 21.34 expected, observed/expected ratio (o/e) 0.89, 90% interval 0.62 to 1.31. The upper end of that interval is the gene's LOEUF score, 1.31, which puts it in group 5 of 6, group 1 being the genes least tolerant of losing a copy. Missense variants: 236 observed, 212.64 expected, observed/expected ratio (o/e) 1.11, 90% interval 1 to 1.24. Synonymous variants: 92 observed, 73.63 expected, observed/expected ratio (o/e) 1.25, 90% interval 1.05 to 1.49.
Homologues: Orthologues: chimpanzee C14H14orf39 (99% identical), macaque C7H14orf39 (94% identical), rabbit C14orf39 (80% identical), dog C14orf39 (79% identical), mouse 4930447C04Rik (69% identical), rat Six6os1 (69% identical), pig C14orf39 (67% identical), guinea pig C14orf39 (64% identical), tropical clawed frog c14orf39 (28% identical).
Diseases named in the same sentence as C14orf39 in open-access papers:
C14orf39 is named in the same sentence as 6 diseases in open-access papers, as found by Europe PMC text mining. Sharing a sentence is not in itself a finding about the gene and the disease. The quoted sentences say what the papers report.
Infertility (6 papers, 2016 to 2025). "Previous studies have linked rare C14orf39 variants to human infertility 48,83,84, 85 and demonstrated associations between common C14orf39 variants and recombination phenotypes 25,44." (PMID 40321295, 2025). "The mutation or loss of C14orf39 can result in defects in chromosome synapsis and meiotic arrest, ultimately leading to infertility." (PMID 40969372, 2025). "Four genes with the most observed LoF variants are SYCE1, C14ORF39, SYCP2, and SYCP3, corresponding to the four reported genes with infertility-related mutations." (PMID 35342360, 2022). "So far, infertility-related mutations have been identified in four SC coding genes, including SYCP2, SYCP3, SYCE1, and C14ORF39." (PMID 35342360, 2022). "So far, infertility-related SC gene mutations are limited to four SC genes (SYCP2, SYCP3, C14ORF39, and SYCE1)." (PMID 35342360, 2022).
glioma (1 paper, 2022). A benign or malignant brain and spinal cord tumor that arises from glial cells (astrocytes, oligodendrocytes, ependymal cells). "Among them, PCOLCE2, ERP27, PSMD13, C14orf39, C16orf86, UGCG, and HPX were identified as prognostic factors for glioma for the first time." (PMID 35873494, 2022).
Obesity (1 paper, 2018). Accumulation of substantial excess body fat. "We observed a nominally significant association for only two T2D markers in RREB1 and PRKAG1, one obesity (OB) marker in the OR2Y1 gene, and for several BMI markers in the ACP1, RBBP6, and C14orf39 genes." (PMID 30126146, 2018).
C14orf39 also shares sentences with these, for which no sentence is quoted: Azoospermia (1 paper); glaucoma (1); pancreatic cancer (1).